BRAF (B-Raf proto-oncogene, serine/threonine kinase)
Diseases named in the same sentence as BRAF in open-access papers (continued):
Sharing a sentence is not in itself a finding about the gene and the disease.
melanoma (continued). "Three of them, DMBC11, DMBC12 and DMBC21 harbored mutation in BRAF (BRAFV600E), the most highly recurrent genetic aberration in melanoma." (PMID 26824319, 2016). "EGFR levels are higher in BRAF-mutant CRCs than in melanomas, explaining why CRCs exhibit EGFR-mediated resistance more frequently." (PMID 27308562, 2016). "While AZD is highly cytotoxic to melanoma from the MSM, the response in patients is varied and seems to be correlated with the BRAF mutation status." (PMID 27339860, 2016). "It was shown that valine is substituted by glutamic acid at position 600 in 90% of BRAF mutant melanomas." (PMID 27042173, 2016). "As melanomas are deregulated via multiple pathways and are able to by-pass mutant BRAF inhibitors to reactivate oncogenic signalling, combination treatment is essential to effectively treat the disease." (PMID 27447557, 2016). "For example, BRAF p.V600E mutant melanomas are extremely sensitive to BRAF inhibition, whereas colorectal cancers with the same mutation show little response." (PMID 26947069, 2016). "Much work on resistance to BRAF inhibition in melanoma has been done, and activation of the parallel PI3k/AKT pathway appears to play an important role." (PMID 26857260, 2016). "Substantial research on BRAF mutant melanoma indicates that BRAF inhibition synergizes with immune checkpoint blockade by facilitating T cell recognition of melanoma antigens in a more favorable tumor microenvironment." (PMID 27959922, 2016). "We demonstrate experimentally that CSF greatly diminishes the responsiveness of BRAF‐mutant melanoma cells to PLX4720." (PMID 26414886, 2016). "SOX10 suppression contributes to BRAF- and/or MEK-inhibitor resistance in BRAF mutated melanoma, by activating TGFβ signalling to upregulate EGFR and PDGFRB, whilst increasing SOX9 transcript abundance has been observed in breast cancer EMT." (PMID 27852308, 2016). "Dabrafenib (GSK2118436) is another potent ATP-competitive inhibitor of BRAF kinase that demonstrated activity in patients with V600E and V600K BRAF-mutant melanoma." (PMID 26981153, 2016). "The authors reported a HPyV6 positive KA, which developed under Vemurafenib therapy in a BRAF V600E positive melanoma patient, with a pronounced viral load." (PMID 27388771, 2016). "They found that BRAF inhibition upregulated autophagy in patients with BRAF-mutant melanoma; these patients were less sensitive to BRAF inhibition and had poorer clinical outcome." (PMID 27583134, 2016). "Collectively, our data demonstrate that there is enormous diversity in the adaptive survival responses to BRAF inhibition utilized by different BRAFV600E melanomas, and that many of the changes observed by molecular profiling are therapeutically irrelevant." (PMID 26673621, 2016). "CLs were also successfully used for topical delivery of BRAF-targeted siRNA to melanoma cells located into the basal epidermis." (PMID 28335259, 2016). "Here we show that BRAF mutant melanoma cells that have developed acquired resistance to BRAF inhibitors display increased oxidative metabolism and increased dependency on mitochondria for survival." (PMID 26365896, 2016). "Nevertheless, BRAF/MEK inhibitor combinations are now accepted as the standard of care for BRAF-mutant advanced melanoma and the trametinib/dabrafenib and cobimetinib/vemurafenib combinations received FDA approval in 2014 and 2015, respectively." (PMID 27200346, 2016). "A secondary aim was to evaluate the usefulness of this combination in BRAF V600E mutant compared to BRAF wild-type melanoma cell lines." (PMID 27783987, 2016). "In recent years BRAF inhibitor drugs have led to significantly improved outcomes for melanoma patients." (PMID 27191502, 2016). "BRAF inhibitors vemurafenib and dabrafenib, selectively block the mutant BRAF protein and prolong overall survival in patients with BRAF mutant melanoma." (PMID 26771141, 2016).
melanoma (continued). "In most of cases in melanomas, MAPK pathway constitutive activation is associated with BRAF activated mutation." (PMID 26828592, 2016). "In BRAF (V600E) mutant melanoma, two phosphorylation sites of LKB (Ser325 and Ser 428), which are crucial for regulation of AMPK activation, are constitutively phosphorylated by ERK and RSK." (PMID 26771234, 2016). "Here, we investigated the effect of combining the BET inhibitor JQ1 with the BRAF inhibitor Vemurafenib in in vitro and in vivo models of BRAF‐mutant melanoma." (PMID 27169980, 2016). "On the other hand, malignant melanoma harboring a mutant BRAF responds to RAF inhibitors, but the tumors often recur within a certain period of treatment." (PMID 27683122, 2016). "The development of BRAFi has been an unprecedented effort that has revolutionized the treatment of BRAF-mutant melanoma." (PMID 27028853, 2016). "Despite the breakthrough that BRAF inhibitors brought to malignant melanoma therapy, major challenges lie ahead toward more effective and longer lasting treatments." (PMID 27648299, 2016). "The ability of ixazomib to inhibit cell proliferation of BRAF wild-type human melanoma cells was evaluated." (PMID 27783987, 2016). "Nivolumab led to a greater proportion of patients achieving an ORR and fewer toxic effects than with alternative available chemotherapy regimens for patients with advanced melanoma that has progressed after ipilimumab or ipilimumab and a BRAF inhibitor." (PMID 26767073, 2016). "A slight increase in the efficacy of ixazomib-induced apoptotic cell death was observed in the BRAF V600E mutant (A375) melanoma cell line compared the BRAF wild-type (WM1366) cell line." (PMID 27783987, 2016). "In our proof-of-principle efficacy study, we demonstrated successful administration of an orally available FDA-approved BRAFV600E inhibitor, Vemurafenib, to adult zebrafish harboring BRAF-mutant melanoma over the 2-week treatment course." (PMID 27482819, 2016). "The mAb W9 defined Grp94 epitope is upregulated on BRAFV600E melanoma cells by incubation with BRAF inhibitor, and with chemotherapeutic agents." (PMID 27461275, 2016). "We also observed that DETS, like resveratrol, down-regulates the expression status of major molecules contributing to melanoma progression, such as BRAF, β-catenin and Brn-2, all of which converge in MITF-M, the master regulator of melanoma signaling." (PMID 27148169, 2016). "Nelfinavir efficiently suppressed PAX3 and MITF expression in a panel of BRAF mutant melanoma cells and reduced the GI50 for the MEK inhibitor selumetinib in drug-tolerant A375 melanoma cells (A375-T) by ∼60-fold, comparable with the GI50 in sensitive cells." (PMID 26977879, 2016). "Consistent with the importance of the Ras-Raf-MAPK pathway activation in melanoma, many somatic missense mutations in genes involved in or regulating this pathway including NRAS, BRAF, MAPKs, and RasGAPs have been identified." (PMID 26993606, 2016). "Targeted therapies with MAPK inhibitors (MAPKi) are faced with severe problems of innate and acquired resistance in BRAF‐mutant melanoma." (PMID 27596438, 2016). "A vast number of mutations, including those of TERT, BRAF, NRAS, PTEN, and CDKN2A, have been linked to the malignant transformation of melanocytes in subgroups of primary melanomas, rendering therapeutic approaches challenging." (PMID 26918341, 2016). "An example of this is a single-base missense transversion causes the replacement of valine with glutamic acid at amino acid residue 600 in BRAF that is detected in about 85% of nevi and melanoma." (PMID 27941674, 2016). "Another BRAF/MEK inhibitor resistance mechanism is based on overexpression of pro-survival factors that allow melanoma cells to evade apoptosis even under complete/efficient ERK inhibition." (PMID 27200346, 2016). "Mice xenografted with a BRAF mutant melanoma treated with digitoxin plus BRAF inhibitor had significantly smaller tumours than mice treated with BRAF inhibitor or digoxin alone." (PMID 27545456, 2016).
melanoma (continued). "To accomplish this, we screened a panel of 12 BRAF mutant melanoma cell lines for drugs or small molecule inhibitors that were synergistically cytotoxic with one of three MAP Kinase pathway inhibitors (PLX4720, RAF265 or PD325901)." (PMID 26673621, 2016). "Herein, we report the case of a melanoma patient treated with sequential BRAF/MEKi (dabrafenib plus trametinib) followed by the anti CTLA-4 antibody ipilimumab who achieved a pathological complete response." (PMID 27447748, 2016). "In the case of BRAF mutant melanoma patients, treatment with BRAF/MEKi has also demonstrated improvements in survival." (PMID 27447748, 2016). "Since we demonstrated that SGI-1776 displays anti-melanoma effects in 3D melanoma models, we investigated the therapeutic value of this agent in vivo using a mutant BRAF model of melanoma." (PMID 27448973, 2016). "The susceptibility to Prima-1, 3-BrPA and NAC in MelJuso cells (BRAF wild-type (wt) and NRAS-Q61L mutant) was compared with that of C8161 melanoma with an enhancing KRAS G12D mutation and a G464E mutation in the BRAF P loop region." (PMID 27863474, 2016). "While MEK inhibitors have shown success in the treatment of BRAF-mutant melanoma, they have shown limited efficacy in RAS-mutant human tumor cell lines and RAS-driven mouse models of cancer." (PMID 27096871, 2016). "In malignant melanoma cells, the oncogene BRAF upholds the activity of glycolysis and therefore the addiction to glycolysis becomes an addiction to BRAF." (PMID 27053249, 2016). "The patient in this study had a BRAF-V600E-mutant melanoma and would be considered to be a strong candidate for VEM as first-line therapy, since VEM targets this mutation." (PMID 27690220, 2016). "We, therefore, identified melanoma patients treated with SRS at our institution and analyzed their outcomes based on BRAF mutation status." (PMID 27200295, 2016). "In melanoma cells, loss of TRIM16 expression is a marker of cell migration and metastasis, while the BRAF inhibitor, vemurafenib, induces melanoma cell growth arrest in a TRIM16-dependent manner." (PMID 27447557, 2016). "Clonogenic growth of resistance BRAF-mutant melanoma cells treated with a combinatory drug therapy using BRAF and MEK inhibitors activate parallel P13K/AKT pathway." (PMID 27746730, 2016). "Another mechanism of resistance is the reactivation of the MAPK pathway through MEK; a recent study explored the effects of MEK and autophagy inhibition in BRAF-inhibitor-resistant melanomas." (PMID 27583134, 2016). "In a mutated BRAF mouse model, ablation of PTEN led to melanoma development, suggesting the PI3K/AKT signaling cascade is one of the critical players in melanomagenesis." (PMID 27941674, 2016). "Specific BRAF inhibitors such as dabrafenib and vemurafenib are the mainstays of treatment in patients with metastatic BRAF-mutant malignant melanomas." (PMID 27255157, 2016). "In conclusion, the combination of a BET inhibitor and a BRAF inhibitor has superior therapeutic potential than either drug alone in in vitro and in vivo models of BRAF‐mutant melanoma." (PMID 27169980, 2016). "BRAF plus MEK inhibitor significantly slowed the growth of BRAF mutant melanomas derived from four patients (M481, M491, M610, M528)." (PMID 27545456, 2016). "All three melanomas that developed metastasis displayed amplification of BRAF at 7q34 (amplicon size, 6 genes), which is a common event in melanoma and it is associated with worse clinical outcome." (PMID 27095580, 2016). "Relapse and aggressive progression of melanoma occurs in most of the patients after 5–7 months of treatment with BRAF inhibitors due to re-activation of MAPK and/or cooperation of PI3K and other alternative signaling pathways." (PMID 26517521, 2016). "We analyzed the value of BRAF V600mut ctDNA from plasma as a monitoring tool for advanced melanoma patients treated with BRAF/MEK inhibitors." (PMID 27095081, 2016).
melanoma (continued). "The majority of melanomas carry mitogen-activated protein kinase (MAPK) pathway-activating mutations, especially in BRAF, NRAS, NF1; providing avenues for targeted therapeutic intervention." (PMID 27009863, 2016). "The A375 (BRAF V600E mutant) human melanoma tumor cell line was used and cells were plated on a six well plate at a density of 2 × 105 cells/well." (PMID 27783987, 2016). "BRAF mutations have been confirmed, not only in LCH, but also in ECD, melanoma, papillary thyroid cancer, colorectal cancer, HCL and CLL." (PMID 27094161, 2016). "In melanoma, the adaptative cell response to BRAF inhibitors includes altered patterns of cytokine production contributing to tumor progression and drug resistance." (PMID 26684239, 2016). "To investigate the utility of this library in the context of drug resistance, we first examined the setting of BRAF-mutant melanoma, one in which acquired resistance to RAF and MEK inhibitors has been well studied." (PMID 27738492, 2016). "We then analyzed progression free survival (PFS) on BRAF inhibitor in a set of 21 BRAF-V600E melanoma patients to determine the relationship of aberrant PTEN and Notch activation with clinical response." (PMID 27655717, 2016). "In particular, these data resemble the metabolic adaptations in BRAF-mutant melanoma cells treated with pathway-specific inhibitors where lactate production is suppressed and mitochondrial protein levels increased." (PMID 27861144, 2016). "In conclusion, we have discovered and characterized CRAF R391W as a novel oncogene for BRAF/NRAS wild type melanomas." (PMID 27273450, 2016). "Other studies suggested that BRAF inhibition leads to increases of tumor infiltrating T cells in melanoma and induces the up-regulation of the melanoma differentiation antigens (MDA) in tumor cells." (PMID 27563819, 2016). "This favorable data clearly established that combination therapy produced superior antitumor efficacy to ipilimumab in patients with BRAF-wildtype melanoma and led to the FDA approval of the combination for this patient population in October 2015." (PMID 26850630, 2016). "For instance, EPHA2 overexpression causes oncogenic transformation of mammary epithelial cells, was found essential for tumour growth and able to mediate resistance to BRAF kinase inhibitors in melanoma." (PMID 27058903, 2016). "With this, the observed differentiation state and phenotypic alteration of the BRAF inhibitor-resistant cells complements previous studies and clearly reflects the common cellular plasticity program of melanoma cells and tumors." (PMID 27648299, 2016). "MITF's contribution to phenotypic heterogeneity and plasticity of melanoma is considered as an important part of reduced sensitivity to the BRAF/MEK/ERK pathway inhibition." (PMID 26824319, 2016). "ZEB1 knockdown in sensitive ZEB1high A375 and SKMEL5 melanoma cells inhibited colony formation in soft agar, to a similar extent to that observed with BRAF inhibition (60%)." (PMID 27596438, 2016). "Here we investigate how metabolism is changed in melanomas that develop acquired resistance to BRAF inhibitors to identify new therapeutic targets for patients who relapse on first‐line targeted therapies." (PMID 26365896, 2016). "The drug Dabrafenib/GSK2118436 with a correlation of 0.881 is in fact a BRAF-targeted drug approved in clinical trial to treat melanoma patients." (PMID 27746730, 2016). "Vemurafenib is an oral BRAF inhibitor which has been shown to increase progression-free and overall survival in patients with advanced melanoma." (PMID 26930506, 2016). "We illustrate the outcomes of a 63 year-old type I diabetic female patient who developed pulmonary metastatic, BRAF wild-type cutaneous melanoma 10 years after renal transplantation." (PMID 27777773, 2016). "In the particular case of melanoma, inhibitors designed to target mutant BRAF fail to produce long-term effects in the clinic owing to the emergence of resistance." (PMID 27583134, 2016).
melanoma (continued). "BRAF-targeting drugs have provided a major breakthrough in melanoma treatment, but have limitations due to high relapse and increased resistance to therapy." (PMID 27829238, 2016). "An important approach to treatment for melanoma is the use of inhibitors such as vemurafenib, dabrafenib, or cobimetinib, which specifically target the mutant BRAF." (PMID 27583134, 2016). "Vemurafenib (Zelboraf, Roche) and dabrafenib (Tafinlar, GlaxoSmithKline) are two BRAF inhibitors, which has been applied in the treatment for melanoma, but the survival rate remains low." (PMID 27556188, 2016). "The rate of cutaneous adverse events associated with vemurafenib was 92% to 95% of patients in the BRAF inhibitor melanoma (BRIM) studies." (PMID 27042173, 2016). "This issue is likely responsible for the differences in ixazomib sensitivity between the BRAF mutant and BRAF wild-type melanoma cell lines used in this study." (PMID 27783987, 2016). "For unresectable melanoma, BRAF/MEK inhibitors and immune check points inhibitors are the first line treatment." (PMID 27582542, 2016). "ERK has emerged as a promising target for melanoma, particularly for melanomas refractory to BRAF and MEK inhibitors using novel ERK inhibitors such as SCH772984, or its clinical analog MK-8353." (PMID 27655717, 2016). "Targeted therapies, including selective BRAF and MEK inhibitors, have improved rates of progression-free and overall survival in patients whose melanoma harbors a BRAF V600 mutation." (PMID 26784231, 2016). "Despite lack of efficacy in in vitro proliferation assays, both honokiol DCA and hexafluoro were both active in vivo against A375 melanoma, a BRAF mutant melanoma xenograft model." (PMID 26871475, 2016). "Utilizing our growing understanding of this disease, we assessed the therapeutic potential of combining RT3D and RT in a panel of melanoma cell lines which included BRAF mutant, Ras mutant and BRAF/Ras wild-type cells." (PMID 27384486, 2016). "These same evaluations were performed in the two different BRAF wild-type human melanoma cell lines, WM1366 and MeWo." (PMID 27783987, 2016). "Four distinct BRAFi were profiled for paradoxical ERK activation across a range of inhibitor doses effective against the BRAF mutant melanoma cell line A375 in vitro." (PMID 27028853, 2016). "Given that acquired resistance to BRAF inhibitors in melanoma is likely due to upregulation of alternative pathways, it is plausible that epigenetic regulation plays a role in acquired resistance." (PMID 26857260, 2016). "Ixazomib treatment induced apoptotic cell death in both BRAF wild-type and BRAF V600E mutant melanoma cell lines." (PMID 27783987, 2016). "Another combined therapy of vemurafenib and cobimetinib in patients with advanced BRAF (V600)-mutant melanomas has also been reported to be promising." (PMID 27270229, 2016). "Targeted therapies with MAPK inhibitors (MAPKi) are faced with severe problems of resistance in BRAF‐mutant melanoma." (PMID 27596438, 2016). "As MEK is frequently hyperactivated in melanomas due to oncogenic BRAF signaling, we also determined the effect of oncogenic BRAF on Pin1-FOXM1 binding." (PMID 26279295, 2016). "In contrast, BRAF-mutant, NF1-deficient, and triple wild-type melanomas were relatively sensitive to these agents." (PMID 27608486, 2016). "Recent studies have identified a role for ROCK inhibition in combinatorial treatments in BRAF-mutant melanoma, as well as in Kras-driven lung cancers." (PMID 26765561, 2016). "Collectively, our data provide a rationale for combined BET and BRAF inhibition as a novel strategy for the treatment of melanoma." (PMID 27169980, 2016). "In vitro studies demonstrate that ERβ agonists can impair melanoma cell proliferation, but this depends on the genetic mutational status (NRAS vs. BRAF) of melanoma cells." (PMID 27833586, 2016).